HP1BP3 (heterochromatin protein 1 binding protein 3)
Description:
Component of heterochromatin that maintains heterochromatin integrity during G1/S progression and regulates the duration of G1 phase to critically influence cell proliferative capacity. Mediates chromatin condensation during hypoxia, leading to increased tumor cell viability, radio-resistance, chemo-resistance and self-renewal.
Synonyms: HP1-BP74; HP1BP74
Tractability: PROTAC: UniProt records ubiquitination sites on it; ubiquitination databases record sites on it; its protein half-life has been measured.
Gene: Protein-coding gene on chromosome 1 (20,739,095 to 20,787,323, reverse strand). Ensembl gene ENSG00000127483.
Subcellular location: Nucleus; Chromosome
Subcellular location (Human Protein Atlas): Nuclear speckles
Gene Ontology:
Molecular function: DNA binding; nucleosome binding; protein binding
Biological process: cellular response to hypoxia; heterochromatin organization; regulation of cell population proliferation; regulation of DNA-templated transcription; regulation of nucleus size; nucleosome assembly
Cellular component: chromosome; nuclear speck; nucleus; nucleosome
Genetic constraint (gnomAD): Loss-of-function variants: 6 observed, 37.06 expected, observed/expected ratio (o/e) 0.16, 90% interval 0.088 to 0.32. The upper end of that interval is the gene's LOEUF score, 0.32, which puts it in group 1 of 6, group 1 being the genes least tolerant of losing a copy. Missense variants: 410 observed, 518.74 expected, observed/expected ratio (o/e) 0.79, 90% interval 0.73 to 0.86. Synonymous variants: 204 observed, 191.12 expected, observed/expected ratio (o/e) 1.07, 90% interval 0.95 to 1.2.
Homologues: Orthologues: chimpanzee HP1BP3 (100% identical), macaque HP1BP3 (99% identical), dog HP1BP3 (96% identical), rabbit HP1BP3 (95% identical), pig HP1BP3 (95% identical), mouse Hp1bp3 (90% identical), rat Hp1bp3 (86% identical), tropical clawed frog hp1bp3 (67% identical), zebrafish hp1bp3 (41% identical).
Diseases named in the same sentence as HP1BP3 in open-access papers:
HP1BP3 is named in the same sentence as 19 diseases in open-access papers, as found by Europe PMC text mining. Sharing a sentence is not in itself a finding about the gene and the disease. The quoted sentences say what the papers report.
postpartum depression (7 papers, 2014 to 2025). A type of clinical depression that occurs after childbirth. "Lower HP1BP3 has been found to be associated with postpartum depression and Alzheimer’s disease in humans." (PMID 30718449, 2019). "In terms of pathogenesis, previous studies have shown that stressful life events can change the epigenetic modification of genes, and women with postpartum depression have different methylation patterns of the hp1bp3 and ttc9b genes." (PMID 38188054, 2023). "Lastly, we will evaluate whether the elevated risk demonstrated by previously identified postpartum depression epigenetic biomarkers in the TTC9B and HP1BP3 genes can be modified with an SB." (PMID 40209215, 2025). "A study of postpartum depression demonstrated that DNA methylation of HP1BP3 and TTC9B could be used as predictors for postpartum depression with ∼80% accuracy." (PMID 35283726, 2022). "DNA methylation variation at HP1BP3 and TTC9B was found to be modified by estrogen exposure in the rodent hippocampus, and postpartum depression was shown to be mediated by differential gene expression and epigenetic sensitivity to pregnancy hormones." (PMID 34263944, 2021).
cognitive deficits (4 papers, 2017 to 2022). "HP1BP3 loss of function is associated with cognitive impairment, suggesting a role for this protein in establishing or maintaining cognitive functions." (PMID 35259090, 2022). "Targeted knockdown of HP1BP3 in the hippocampus induced cognitive deficits." (PMID 31805863, 2019). "As a result, we can now better understand how misregulation of Hp1bp3 may contribute to cognitive impairments seen in both Hp1bp3 knockout mice and cognitively impaired aging mice and humans with decreased levels of Hp1bp3." (PMID 30549219, 2019). "Here, we provide a mechanistic explanation for these findings and show that targeted knockdown of Hp1bp3 in the hippocampus by 50%–75% is sufficient to induce cognitive deficits and transcriptional changes reminiscent of those observed in aging and Alzheimer's disease brains." (PMID 30549219, 2019).
Alzheimer disease (2 papers, 2019). A progressive, neurodegenerative disease characterized by loss of function and death of nerve cells in several areas of the brain leading to loss of cognitive function such as memory and language. "Many alterations observed after Hp1bp3 KD appear to phenocopy alterations observed in aging and Alzheimer's disease (AD)." (PMID 30549219, 2019).
depression (2 papers, 2019 to 2024). "For example, one study identified DNA methylation in antenatal TTC9B and HP1BP3 genes, which can predict with 80% accuracy whether a woman will develop depression in the postpartum period." (PMID 39247639, 2024).
aging (1 paper, 2019). A developmental process that is a deterioration and loss of function over time. "Recent studies have demonstrated that long‐term maintenance of chromatin structure is critical for maintenance of cognitive longevity (Lopez‐Otin, Blasco, Partridge, Serrano, & Kroemer, 2013), providing an additional mechanism Hp1bp3 may work through in order to influence cognitive aging." (PMID 30549219, 2019).
bladder cancer (1 paper, 2024). "Glycosyltransferase, C1GALT1, is controlled in bladder cancer (BLCA) by the cHP1BP3 (circRNA produced from HP1BP3) –miR-1-3p axis, which represses and decreases the migratory ability and proliferation of BLCA cells in vitro and in vivo by altering target glycoproteins." (PMID 38191389, 2024).
dwarfism (1 paper, 2019). "HP1BP3 is highly expressed in the brain and is related to a number of physical and behavioral phenotypes in mice, such as dwarfism, impaired bone mass, impaired maternal behavior, and anxiety." (PMID 30718449, 2019).
esophageal carcinoma (1 paper, 2024). A primary or metastatic malignant neoplasm involving the esophagus. "Moreover, HP1BP3 promotes esophageal carcinoma metastasis by upregulating miR-23a." (PMID 39201614, 2024).
glioma (1 paper, 2024). A benign or malignant brain and spinal cord tumor that arises from glial cells (astrocytes, oligodendrocytes, ependymal cells). "HP1BP3 is overexpressed in thyroid or prostate carcinoma and in a few glioma types." (PMID 39201614, 2024).
tumor (4 papers, 2016 to 2023). "Six upregulated and mutated tumor antigens related to NMD, and infiltration of APCs were identified in patients with BLCA, including HP1BP3, OSBPL9, SSH3, ZCCHC8, FANCI, and EIF4A2." (PMID 36761744, 2023). "Six tumor antigens (HP1BP3, OSBPL9, SSH3, ZCCHC8, FANCI and EIF4A2) were correlated with the expression of NMD factors and infiltration of APCs, which may be promising candidates for mRNA vaccines." (PMID 36761744, 2023).
infection (2 papers, 2018 to 2023). The state of being infected such as from the introduction of a foreign agent such as serum, vaccine, antigenic substance or organism. "Consistent upregulation of HP1BP3 in our infection groups suggests an aggrandized phenomenon of epigenetic gene suppression of the targeted immune-responsive genes." (PMID 38138142, 2023).
cancer (1 paper, 2024). A tumor composed of atypical neoplastic, often pleomorphic cells that invade other tissues. "In cancer tissues, HP1BP3 is involved in the adhesion of malignant cells to collagen." (PMID 39201614, 2024).
metabolic disease (1 paper, 2020). A congenital disorder (due to inherited enzyme abnormality) or acquired (due to failure of a metabolically important organ) disorder resulting from an abnormal metabolic process. "In addition, we found that many genes are related to metabolic diseases, such as AKT was involved in glucose metabolism, APOA1 was related to lipid metabolism, and HP1BP3 seem to be associated with thyroid disease." (PMID 33067549, 2020).
HP1BP3 also shares sentences with these, for which no sentence is quoted: age (1 paper); bacterial infections (1); cognitive decline (1); lymphoma (1); mood disorder (1); prostate carcinoma (1).